GHR (growth hormone receptor)
Diseases named in the same sentence as GHR in open-access papers (continued):
Sharing a sentence is not in itself a finding about the gene and the disease.
polycythemia vera (1 paper, 2019). "One was a very rare missense variant in JAK2 (p.E890K; MAF = 0.08%), which is the causative gene of polycythemia vera (MIM: 263300) and thrombocythemia-3 (MIM: 614521) and is activated by the binding of a growth hormone to a growth hormone receptor." (PMID 31562340, 2019).
prostate tumours (1 paper, 2014). "Patterns of GHR autoregulation may partially account for differences between prostatic cell lines and, by extension, prostate tumours." (PMID 25580121, 2014).
reflux esophagitis (1 paper, 2016). "(2010) studied IGF Axis Polymorphisms and reported SNPs in three genes (IGF1, IGF1R, and GHR) to be associated with BE, EAC, or reflux esophagitis." (PMID 27468417, 2016).
renal fibrosis (1 paper, 2022). A final common manifestation of a wide variety of chronic kidney diseases characterized by glomerulosclerosis and tubulointerstitial fibrosis. "We found that SLC4A1, THY1, and GHR were significantly under-expressed in renal fibrosis, and PLA2G4A and EGR1 were significantly over-expressed compared with the normal group." (PMID 36120336, 2022).
thymic atrophy (1 paper, 2026). "Preservation of age-associated thymic atrophy in GHR-/- mice might be responsible for the continuous production of naïve T cells, and maintenance of lymphoid-to-myeloid homeostasis to mount an effective immune response." (PMID 41524828, 2026).
Trypanosoma cruzi infection (1 paper, 2023). "In the current ex vivo study, we employed serum from GHR-/- mice, also known as LS mice (a model of GH resistance with high GH and low IGF-1 levels), and serum from bovine GH (bGH) transgenic mice (high GH and IGF-1), to test the effect on Trypanosoma cruzi infection." (PMID 37163287, 2023).
undifferentiated carcinoma (1 paper, 2015). A usually aggressive malignant epithelial neoplasm composed of atypical cells which do not display evidence of glandular, squamous, or transitional cell differentiation. "A tendency for decreased GHR expression was also noted, particularly in undifferentiated carcinomas, which showed heterogeneous immunoreactivity compared to diffuse staining in normal tissue and benign tumors." (PMID 26370564, 2015).
urothelial carcinoma (1 paper, 2025). A malignant neoplasm derived from the transitional epithelium of the urinary tract (urinary bladder, ureter, urethra, or renal pelvis). "In this study, we investigated the impact of GH and its receptor (GHR) on therapy resistance and disease progression in urothelial carcinoma (UC) through integrated transcriptomic and in vitro analyses." (PMID 40806252, 2025).
vascular malformation (1 paper, 2023). A non-neoplastic disorder that is the result of defects of vascular morphogenesis. "GHR was found in the endothelial/perivascular area of vascular malformations, and also in the stroma of control tissues." (PMID 37864259, 2023). "Their finding of GHR expression is in line with our findings in the present study, supporting the view that GH may have a role in the expansion of vascular malformations." (PMID 37864259, 2023). "Several studies have demonstrated that specific hormone receptors (HR) such as progesterone receptor (PGR), growth hormone receptor (GHR), and follicle-stimulating hormone receptor (FSHR) were present in vascular tumors and vascular malformations." (PMID 37864259, 2023). "In these studies, expression of GHR, FSHR, and PGR was reported mostly in endothelium of vascular malformations." (PMID 37864259, 2023).
ZIKV infection (1 paper, 2021). "Among the top selected differentially expressed genes, such as PTBP1, LIF, GHR, PTBP3, EDNRB, and MBP, the mRNA and protein expressions were confirmed to identify the dysregulation of the transcriptome in MPAs upon ZIKV infection." (PMID 33891593, 2021). "We found that PTBP1, LIF, GHR, and PTBP3 were upregulated while EDNRB and MBP were downregulated upon ZIKV infection." (PMID 33891593, 2021). "Our results showed that mRNA levels of PTBP1, LIF, PTBP3, and GHR were significantly upregulated, while EDNRB and MBP were downregulated upon ZIKV infection at indicated time." (PMID 33891593, 2021).
Zinc deficiency (1 paper, 2023). A deficiency of the essential metal Zinc; an essential cofactor for many enzymes. "Zinc deficiency in chicken feed has a negative impact on growth, feed consumption, and the production of insulin-like growth factor-I, growth hormone binding protein, and growth hormone receptor." (PMID 36770731, 2023).
cancer (94 papers, 2006 to 2026). A tumor composed of atypical neoplastic, often pleomorphic cells that invade other tissues. "Based on the empirically established role of GH in cancer progression, our findings reveal that elevated tumoral GHR expression in NSCLC is associated with the upregulation of gene signatures involved in key oncogenic processes." (PMID 41515995, 2025). "GHR is a membrane-bound receptor belonging to the class I cytokine receptor superfamily, which has been implicated in the development of many types of cancer." (PMID 37542549, 2023). "GHR, a member of the class I cytokine receptor family, plays a critical role in cancer development, and is associated with cancer chemoresistance as well as metastasis." (PMID 32970612, 2020). "Accordingly, patients with acromegaly, who have high GH plasma levels, show a higher incidence of cancer, while patients with Laron syndrome who are resistant to GH due to a defective GHR and patients with GH deficiency have reduced cancer susceptibility." (PMID 33260481, 2020). "Elaborate studies by us and others have identified a direct association of GH and EMT in GHR expressing human cancers." (PMID 32382711, 2019). "Among the downregulated genes, GHR is a novel observation as most studies associate GHR over-expression as a risk factor for cancer." (PMID 29324814, 2018). "Patients with LS, who have inactivating mutations in the GHR gene, are obese and resistant to diabetes and cancer." (PMID 28670222, 2017). "GHR stimulation can promote cell invasion and metastasis and GHR deficiency down-regulates the incidence of cancer." (PMID 27825319, 2016). "In humans, mutations in growth hormone receptor genes have been found to be associated with lower cancer risk." (PMID 26056364, 2015). "For example, disruption of the growth hormone receptor (GHR) in mice extends lifespan >40 %,9 yet GHR deficiency in humans does not result in reduced mortality, even if it appears to protect from cancer." (PMID 25486354, 2014). "Additionally, GHR is expressed by many types of cells in the tumor microenvironment, including tumor cells, cancer-associated adipocytes, cancer-associated fibroblasts, immune cells, stromal cells, and endothelial cells." (PMID 40806252, 2025). "However, nuclear GHR localisation has also been observed and is associated with increased cancer cell proliferation." (PMID 37043098, 2023). "It is believed that in cancer cells, binding of GH with GHR activates receptor associated intracellular domain such as JAK2, which further accelerate activation of oncogenic transcription factors STAT3 and STAT5, and other survival molecules including IRS-1, AKT, and ERK." (PMID 36276070, 2022). "Also, long-term follow-up studies with the Israeli and Ecuadorian cohorts of individuals with Laron Syndrome (LS) (GH resistant due to dysfunctional mutations in GHR) remarkably find them to be completely resistant to all cancers." (PMID 35865483, 2022). "Recently, GHR has been reported to be associated with various types of cancer." (PMID 33492754, 2021). "Additionally, upregulation of GHR levels have been reported to increase the risk of cancer in general and regulate key cellular functions, such as metastasis, apoptosis, proliferation, and differentiation." (PMID 33891593, 2021). "A previous study has demonstrated that GHR deficiency results in reduced risk for death from cancer, suggesting that GHR may be used as a therapeutic target for cancer treatment." (PMID 32069380, 2020). "Drugs interfering with GHR activity might inhibit the spread of cancer while making existing cancer cells more susceptible to treatment." (PMID 30617282, 2019). "GHR gene knockout pigs could also provide further insight into cancer and life expectancy in patients with GHR mutations." (PMID 26511035, 2015).
cancer (continued). "Likewise, it is also worth noting that SEPP1 is located at chromosome position 5p13.1, close to chromosomal regions that contain the growth hormone receptor and alpha-methylacyl-CoAracemase, genes of potential relevance to cancer susceptibility." (PMID 17156480, 2006). "Notably, patients with Laron syndrome, who have GHR gene deficiency, rarely develop cancer." (PMID 36276070, 2022). "For example, genome studies of the longest-lived bat Myotis brandtii showed that cancer resistance might be attributed to growth suppression by specific mutations in the growth hormone receptor that may reduce the GH-insulin-like growth factor 1 signalling pathway." (PMID 31249297, 2019). "It is well known that GHR regulates many cellular pathways involved in survival, proliferation, metastasis, epithelial to mesenchymal transition, apoptosis and cell cycle, but its hyperactivation may increase the risk of cancer in general." (PMID 29932147, 2018). "GHR antagonism can reverse these effects and thus improve antineoplastic efficacy, as observed in other types of human cancer." (PMID 41515995, 2025). "For example, mice that are transgenic for GH have increased incidence of cancer and tumor burden, while mice with an inactivating disruption in the GHR gene have decreased incidence of cancer and tumor burden." (PMID 40806252, 2025). "Based on the empirically demonstrated role of GH in other cancer studies, we identified that GHR antagonism in PDAC leads to suppression of the gene signature of hallmark cancer processes." (PMID 39000545, 2024). "Over the last decade, abrogation of growth hormone (GH) action by targeting the GH receptor (GHR) to specifically curb cancer chemoresistance has shown promising in vivo results in multiple human cancer models." (PMID 39000545, 2024). "GHR antagonists (GHRAs) can effectively reduce tumor growth, but more importantly, improve treatment efficacy of anti-cancer compounds in both male and female mouse xenograft models." (PMID 39000545, 2024). "The growth hormone (GH)–GH receptor (GHR) pair is a covert driver of multimodal therapy resistance in cancer and is overexpressed in PDAC tumors, yet the therapeutic potential of targeting the same has not been explored." (PMID 39000545, 2024). "A global reduction in GHR expression led to improved insulin sensitivity, a reduction in cancer and an extension of lifespan in mice." (PMID 37881503, 2023). "Recently, the contribution of GHR signaling to the development, survival, and progression of cancer has gained increasing attention." (PMID 36276070, 2022). "Using a syngeneic mouse model of HCC with Hepa1-6 implants and sorafenib treatment in GHA vs. WT mice, we confirmed that GHR antagonism can significantly enhance therapeutic success in cancers expressing the GHR." (PMID 35865483, 2022). "When we further analyzed GRHR-related pathways, we found that GHR was highly expressed in a large number of cancer-related pathways and related to some m6A regulators, as well as PIM1." (PMID 35928449, 2022). "Many types of human cancers express GH, GHR, IGF-I, and/or IGF-IRs in the tumour or the tumour microenvironment, thus providing an opportunity for GH/IGF-I to act in an endocrine, paracrine, or autocrine manner." (PMID 35319491, 2022). "We report that isomiR-21-5p | ±1 regulates GHR, possibly acting as a tumor suppressor that is often downregulated in cancers." (PMID 35729324, 2022). "GHR gene is located on the fifth chromosome and is highly expressed in many types of human cancers, such as colorectal carcinoma and breast cancer." (PMID 33492754, 2021). "The activation of GH and its receptor GHR can promote the development of various cancers by enhancing cell proliferation, invasion, and migration and inhibiting cell apoptosis." (PMID 34178997, 2021). "Growth hormone receptor (GHR), a member of the class I cytokine receptor family, plays key roles in cancer progression." (PMID 32069380, 2020).
cancer (continued). "Our study reveals that GH action renders an intrinsic drug resistance phenotype to the melanoma tumors—a clinically crucial property of GH verifiable in other human cancers with GHR expression." (PMID 33291663, 2020). "On the other way, GHR-KO mice exhibit an excessive fat deposition, but they have the ability to resist metabolic deterioration inducted by HFD and reduce cancer risk." (PMID 33519913, 2020). "This is supported by the fact that several cancers express GH receptors (GHR), and GHR positivity is predictive of a worse outcome." (PMID 33260481, 2020). "GHR is widely distributed in various types of normal and tumor cells with different expression levels, and plays an important role in cancer progression." (PMID 32069380, 2020). "GHR was a member of the class I cytokine receptor family which played key roles in cancer progression." (PMID 33330065, 2020). "The existing body of evidences justify GHR-antagonism as a viable approach as monotherapy in cancer." (PMID 32382711, 2019). "Here, we exclusively zoom in on this critical aspect of GH signaling in GHR-positive human cancers, which appears to point toward a novel target towards tackling malignant cancer subtypes." (PMID 32382711, 2019). "Pegvisomant, as an existing example of a GHR-antagonist, can be combined with specific anti-cancer therapeutic approaches to improve treatment efficacy." (PMID 32382711, 2019). "In conclusion, the present study provides a valuable mechanistic insight into therapy resistance regulation by GH and GHR in human cancers." (PMID 31547367, 2019). "We refer our readers to a series of relevant reviews by us and colleagues in this regard, compiling the systematic comprehension of the overall and molecular details of how GHR-positive cancer cells exploit the versatile effects of GH action." (PMID 32382711, 2019). "Collectively, these results do establish a stem-cell promoting property of GH in cancer and warrant further in vivo studies in GHR-overexpressing cancers like melanoma, thwarted by drug-resistance, relapse and high mortality." (PMID 32382711, 2019). "Collectively these results bolster the fact that GH action is protective against radiotherapy in human cancers and that functional GH antagonism using a GHR-antagonist helps to sensitize the cancer to IR treatment." (PMID 32382711, 2019). "Silencing the gene for GHR dramatically reduced the ability of the cells to multiply and spread, and also reduced the cells’ resistance to anti-cancer drugs." (PMID 30617282, 2019). "GH and its cognate receptor (GHR) are expressed in several forms of cancer and have been validated as an anti-cancer target through a large body of in vitro, in vivo and epidemiological analyses." (PMID 32382711, 2019). "Our current understanding of GH mediated cancer therapy resistance is a function of GHR hyperactivation due to increased autocrine/paracrine as well as endocrine GH." (PMID 32382711, 2019). "It should be noted that the downregulation of GHR gene in ONB was an unexpected result, as most studies in the literature associate GHR upregulation with increased cancer risk." (PMID 29324814, 2018). "Over the last few decades, the tumor driving properties of GH and GHR had been established in cancers of the breast, colon and prostate." (PMID 28223541, 2017). "It is possible, that elimination of cells by apoptosis protects OSE from cancer development and corresponds to the lower incidence of cancer in GHR-KO mice, with very low levels of IGF-1 in circulating plasma." (PMID 24063422, 2013). "Targeting GHR in multiple types of human cancers has been hypothesized and shown to significantly attenuate tumor resistance to multiple antineoplastic approaches, including radiation therapy, chemotherapy, targeted therapy, and immunotherapy." (PMID 39000545, 2024). "Remarkably, patients with defective GHR signaling caused by an inactivating mutation of the GHR, as found in Laron dwarfism, do not develop cancer." (PMID 39459020, 2024).